P2RX7 (purinergic receptor P2X 7)
Description:
ATP-gated nonselective transmembrane cation channel that requires high millimolar concentrations of ATP for activation. Upon ATP binding, it rapidly opens to allow the influx of small cations Na(+) and Ca(2+), and the K(+) efflux. Also has the ability to form a large pore in the cell membrane, allowing the passage of large cationic molecules. In microglia, may mediate NADPH transport across the plasma membrane. In immune cells, P2RX7 acts as a molecular sensor in pathological inflammatory states by detecting and responding to high local concentrations of extracellar ATP. In microglial cells, P2RX7 activation leads to the release of pro-inflammatory cytokines, such as IL-1beta and IL-18, through the activation of the NLRP3 inflammasome and caspase-1. Cooperates with KCNK6 to activate NLRP3 inflammasome (By similarity). Activates death pathways leading to apoptosis and autophagy. Activates death pathways leading to pyroptosis (By similarity). [Isoform B]: Shows ion channel activity but no macropore function. [Isoform H]: Non-functional channel. [Isoform J]: Non-functional channel.
Synonyms: P2X7; MGC20089
Tractability: Small molecule: a drug acting on it is in phase 2 or 3 trials; a high-quality ligand is known; it belongs to a druggable protein family. Antibody: UniProt places it where antibodies can reach, with high confidence; its Gene Ontology location is reachable by antibodies, with high confidence; UniProt predicts a signal peptide or a membrane-spanning region. PROTAC: its protein half-life has been measured; a small molecule that binds it is known.
Target class: Ligand-gated ion channel; P2X receptor; Ion channel
Safety:
Unwanted effects reported when the protein is acted on. In parentheses: how it was acted on, where the effect was seen, and who reports it.
decreased convulsions (inhibition, acute dosing; nervous system, renal, immune; source: Lynch et al. (2017))
decreased inflammation (inhibition, acute dosing; nervous system, renal, immune; source: Lynch et al. (2017))
decreased pain (inhibition, acute dosing; nervous system, renal, immune; source: Lynch et al. (2017))
hemolysis (activation, acute dosing; nervous system, renal, immune; source: Lynch et al. (2017))
increased pain (activation, acute dosing; nervous system, renal, immune; source: Lynch et al. (2017))
increased urinary sodium excretion (activation, acute dosing; nervous system, renal, immune; source: Lynch et al. (2017))
increased urine excretion (activation, acute dosing; nervous system, renal, immune; source: Lynch et al. (2017))
neurodegeneration (activation, chronic dosing; nervous system, renal, immune; source: Lynch et al. (2017))
Gene: Protein-coding gene on chromosome 12 (121,132,819 to 121,188,032, forward strand). Ensembl gene ENSG00000089041.
Subcellular location: Cell membrane
Pathways (Reactome):
Hemostasis: Elevation of cytosolic Ca2+ levels; Platelet homeostasis
Cellular responses to stimuli: Mechanical load activates signaling by PIEZO1 and integrins in osteocytes
Disease: Purinergic signaling in leishmaniasis infection
Immune System: The NLRP3 inflammasome
Gene Ontology:
Molecular function: extracellularly ATP-gated monoatomic cation channel activity; potassium channel activity; protein binding; purinergic nucleotide receptor activity; sodium channel activity; ATP binding; identical protein binding; lipopolysaccharide binding; signaling receptor binding; channel activity; monoatomic ion channel activity; signaling receptor activity
Biological process: bleb assembly; membrane depolarization; negative regulation of cell volume; plasma membrane phospholipid scrambling; pore complex assembly; positive regulation of bleb assembly; positive regulation of calcium ion transport into cytosol; positive regulation of gene expression; positive regulation of glycolytic process; positive regulation of interleukin-1 beta production; positive regulation of monoatomic ion transmembrane transport; protein homotrimerization; purinergic nucleotide receptor signaling pathway; response to ATP; apoptotic signaling pathway; calcium ion transmembrane transport; calcium-mediated signaling; cell surface receptor signaling pathway; cellular response to ATP; extrinsic apoptotic signaling pathway; negative regulation of bone resorption; negative regulation of MAPK cascade; positive regulation of bone mineralization; positive regulation of cytoskeleton organization; positive regulation of NLRP3 inflammasome complex assembly; and 11 more
Cellular component: membrane; plasma membrane; bleb; cytoplasm; cell-cell junction; external side of plasma membrane; neuromuscular junction; neuronal cell body; postsynapse; synapse
Genetic constraint (gnomAD): Loss-of-function variants: 49 observed, 64.88 expected, observed/expected ratio (o/e) 0.76, 90% interval 0.6 to 0.96. The upper end of that interval is the gene's LOEUF score, 0.96, which puts it in group 4 of 6, group 1 being the genes least tolerant of losing a copy. Missense variants: 621 observed, 690.26 expected, observed/expected ratio (o/e) 0.9, 90% interval 0.84 to 0.96. Synonymous variants: 268 observed, 260.81 expected, observed/expected ratio (o/e) 1.03, 90% interval 0.93 to 1.14.
Homologues: Orthologues: chimpanzee P2RX7 (99% identical), macaque P2RX7 (93% identical), pig P2RX7 (88% identical), dog P2RX7 (86% identical), rabbit P2RX7 (86% identical), mouse P2rx7 (81% identical), rat P2rx7 (80% identical), guinea pig P2RX7 (77% identical), tropical clawed frog p2rx7 (43% identical), zebrafish p2rx7 (43% identical). Paralogues in human: P2RX4 (30% identical), P2RX1 (27% identical), P2RX3 (25% identical), P2RX2 (24% identical), P2RX6 (24% identical), P2RX5 (23% identical).
Diseases named in the same sentence as P2RX7 in open-access papers:
P2RX7 is named in the same sentence as 365 diseases in open-access papers, as found by Europe PMC text mining. Sharing a sentence is not in itself a finding about the gene and the disease. The quoted sentences say what the papers report.
depression (74 papers, 2009 to 2026). "Polymorphisms in the P2RX7 gene have repeatedly been associated with psychiatric disorders including major depression." (PMID 40024982, 2025). "The Gln460Arg polymorphism of the P2RX7 gene is associated with the severity of depression symptoms." (PMID 38642324, 2025). "P2RX7 is associated with the inflammatory response and neuroimmune mechanisms of depression and neurodegenerative diseases." (PMID 36520780, 2022). "In genetic studies, single nucleotide polymorphisms (SNPs) in the P2RX7 gene haven been linked to brain disorders such as depression, Alzheimer’s disease, or bipolar disorder." (PMID 35422688, 2022). "Moreover, a recent proteome-wide association study identified P2RX7 among 25 brain-expressed proteins causally linked to depression, providing additional support for the involvement of this receptor in affective disorders." (PMID 40713568, 2025). "Several chromosomal regions may be involved in the development of mood disorders, such as purinergic receptor family member P2X7 (P2rx7) gain-of-function polymorphism, the role of which in the development of major depression remains controversial." (PMID 37908978, 2023). "Stress is a major environmental etiological factor in mood disorders, and P2RX7 activation has been associated with an inflammatory and stress-mediated depression-like phenotype with enhanced IL-1β release contributing to stress-induced depression." (PMID 34111150, 2021). "Genetic association studies of P2RX7 variants with depression have been inconclusive." (PMID 34111150, 2021). "Synthesising findings from several animal studies it has been hypothesised that P2RX7 in interaction with stress predisposes to depression via profound effects on several processes interacting with environmental factors through the life span." (PMID 34111150, 2021). "We also demonstrated applicability of the HADS questionnaire in our previous genetic association findings, e.g. reporting association between polymorphisms of the P2RX7 gene and depression scores of diabetic patients and patients with major depression or bipolar disorder." (PMID 24324616, 2013). "Interestingly, one P2X ion channel (P2RX7) has been identified by a number of studies as having polymorphic sites (SNPs), which are associated with bipolar disorder and major depressive disorder in a large number of patients." (PMID 21897848, 2011). "Mice exposed to chronic unpredictable stress or chronic restraint stress showed enhanced P2RX7 expression in the frontal cortex and hippocampus, while the absence of the gene caused increased stress resilience and a phenotype with alleviated depression-like characteristics." (PMID 40429831, 2025). "Our study is the first to investigate several variants in the P2RX7 gene and in interaction with two types of stress, extending our understanding of neuroinflammation in depression, and supporting that the majority of genes influence depression by enhancing sensitivity to stressors." (PMID 34111150, 2021). "Emerging evidence positions the P2RX7 as a key mediator at the intersection of neuroinflammation and stress-related psychiatric conditions, including depression and anxiety." (PMID 40429831, 2025). "Clinical studies have linked it to rapid cycling in bipolar disorder type 1, where P2RX7 expression was found to be modulated by sleep deprivation and also to major depression." (PMID 40713568, 2025). "A fourth P2rx7 KO mouse, developed at Shanghai University using CRISPR/Cas9 technology, revealed that P2X7 protects from viral infection and that P2X7 contributes to depression as mice age." (PMID 37175933, 2023). "A third P2rx7 KO mouse, developed by Lexicon Genetics for Abbott Laboratories, revealed a role for P2X7 in depression." (PMID 37175933, 2023). "Several animal experiments on rodents, have demonstrated the involvement of P2rx7 in the pathophysiology of depression." (PMID 37908978, 2023).
depression (continued). "In fact, P2RX7 is now being investigated in major depressive disorder as a potential novel therapeutic target with several brain-penetrating antagonists in phase 2 and 3 clinical trials." (PMID 34111150, 2021). "We investigated the effect of several variations in P2RX7 gene using a clumping method in interaction with early adversities and recent stress on depression severity." (PMID 34111150, 2021). "The P2X purinoceptor 7 (P2RX7) mediates inflammatory microglial responses and is implicated in neuroimmune mechanisms of depression and neurodegenerative disorders." (PMID 34111150, 2021). "The potential role of P2RX7 in depression is also reflected by the fact that its activity and hippocampal expression is selectively modulated by different antidepressants and by stress exposure." (PMID 34111150, 2021). "Main effects and interactions with childhood adversities (CHA) and recent life events (RLE) of P2RX7 tops SNPs rs74892325 and rs61953400 on current depression symptom severity." (PMID 34111150, 2021). "There have been a number of genetic studies over the last decade linking a SNP in the human P2RX7 gene to depression, anxiety, and bipolar disorder." (PMID 26217184, 2015). "Furthermore, the results suggesting that P2RX7 variation has an effect on depression only in interaction with stress is in alignment with rodent models that explore humanized hP2rx7 mice in a gene–environment interaction scenario." (PMID 40429831, 2025). "Based on these data, our primary goal was to investigate whether P2rx7 plays a role in the mechanism of action of zinc in modulating depression-like behavior in mice in the TST and FST." (PMID 37908978, 2023). "Over the past decades, research has unveiled the pivotal involvement of the P2RX7-Gln460Arg receptor in a wide range of pathological and physiological processes, including severe sepsis, osteoporosis, bipolar disorder, major depressive disorder, and infections." (PMID 37894166, 2023). "However, there is scarce evidence about the alterations in P2RX7 or P2RX4 levels and in behavioral consequences induced by previous exposure to stress, a major risk factor for depression in humans." (PMID 31656696, 2019). "In contrast there are several genetic studies that do not find an association with P2RX7 genotype at this polymorphic site and bipolar disorder, major depression or schizophrenia." (PMID 26217184, 2015). "We did not detect significant association of P2RX7 gene rs2230912 polymorphism with unipolar depression (P>0.05)." (PMID 24533115, 2014). "However, a genome-wide association study, which identified risk variants for depression and bipolar disorder with genome-wide significance, did not detect any association related with the P2RX7 gene." (PMID 35422688, 2022). "Given our increasing understanding that the majority of genes implicated as etiological factors in the development of depression have a role in mediating response to stressors rather than directly influencing risk, P2RX7 may be an especially relevant target." (PMID 34111150, 2021). "Excessive activation of P2RX7 and NLRP3 leads to increased inflammatory cytokine secretion, such as IL-1β in depression and diabetes." (PMID 32842536, 2020). "Our findings also provided initial evidence of possible dysregulation in 3 relatively novel targets for depression: ion channels TRPV1, P2RX7 and P2RY1." (PMID 24143878, 2013). "Excessive/sustained release of ATP during stress exposure could trigger the activation of P2RX7 and/or P2RX4 in brain regions important for stress and depression." (PMID 31656696, 2019). "Of the 9 ion channel receptors that we examined, P2RX7, TRPV1, and P2RY1 were upregulated in female patients during a depressive episode, and P2RY1 expression was positively related to depression severity along with 2 other ion channel receptors, TRPV4 and P2RX1." (PMID 24143878, 2013).
depression (continued). "In general, TRD and drug-free patients had similarly increased levels of inflammation-related genes: this applied to both the genes that had been measured before in depression (IL1-beta, IL-6, TNF-alpha and MIF) and those never measured before (A2M, CRP, P2RX7, CCL2 and STAT1)." (PMID 32699209, 2020).
breast carcinoma (48 papers, 2012 to 2025). "Breast cancer patients carrying loss-of-function alleles of P2RX7-E496A (rs3751143) exhibit reduced therapeutic efficacy of adjuvant chemotherapy." (PMID 38195677, 2024). "The local consistencies of genes 3636 (INPPL1) and 5027 (P2RX7) were also found to be negatively associated to breast cancer survival." (PMID 31874600, 2019). "Abrogation of P2RX7 has been associated with decreased response to foreign material in graft versus host models, increased metastatic potential in human breast cancer and increased susceptibility to colon and epithelial cancers." (PMID 27171399, 2016). "P2RX7 (Glu496Ala) mutations in breast cancer patients receiving anthracycline therapy were associated with significantly lower metastasis free survival compared to patients bearing normal P2RX7 alleles." (PMID 26486085, 2015). "P2RX7 high expression in MDA-MB-435 cells (an invasive human breast cancer cell line) activated pro-migratory phenotype and invasiveness by releasing extracellular matrix-degrading proteases in vitro and in vivo." (PMID 36741002, 2023). "While loss-of-function mutations affecting TLR4 or P2RX7 have a negative impact on the survival of breast cancer patients, local expression of MX1 constitutes a positive prognostic marker." (PMID 26369701, 2015). "In breast cancer cell lines of MCF-7 and MDA-MB-231, increasing P2RX7’s expression in tumor cells maintains tumor cell survival and invasion ability by activating ERK1/2 and Akt pathways." (PMID 41007849, 2025). "Tumors grew faster in p2rx7−/− mice, and P2RX7 inhibition induced apoptosis in colorectal cancer cells and the MCF7 breast cancer model." (PMID 36741002, 2023). "Given the crucial role of P2X7 receptor in immune modulation, P2RX7 SNPs have been studied in several types of cancers like breast cancer, chronic lymphocytic leukemia, nasopharyngeal carcinoma, and papillary thyroid cancer." (PMID 27779103, 2016). "By using P2rx7+/+ and P2rx7−/− mice, we demonstrated that, in the syngeneic and orthotopic model of mammary cancer, there is no participation of the P2X7R in the host organism in either anti- or pro-tumour activities." (PMID 32825056, 2020). "Remarkably, we found that multiple genes that belong to the NLRP3 inflammasome pathway, including P2rx7, Nlrp3, Casp1, Il1a and Il1b are upregulated in CAFs isolated from mammary carcinoma, but not in normal mammary tissue, or in fibroblasts isolated from mammary hyperplasia." (PMID 31558756, 2019).
Sepsis (44 papers, 2014 to 2025). Sepsis is defined as life-threatening organ dysfunction caused by a dysregulated host response to infection. "There is evidence for the function of P2X7R signaling in energy metabolism, fat mass and weight gain, and it is likely that this impacts the association between P2RX7 SNPs and sepsis." (PMID 38966639, 2024). "P2rx7-deficient mice present aggravated damage to different organs and premature deaths during sepsis and the administration of recombinant CD14 restores survival in the P2rx7−/−genotype mice." (PMID 33135636, 2020). "The contribution of P2RX7 in metabolic syndrome has received the most attention, causing hepatocyte apoptosis in mice with a high-fat diet and inducing macrophage-mediated inflammation in sepsis-induced liver injury." (PMID 37046119, 2023). "In the context of likely different P2RX7 genotypes linked to functional phenotypes that manifest in sepsis versus successful control of respiratory diseases, a future clinical study should be initiated to selectively compare cases with pneumonia independently from sepsis." (PMID 38966639, 2024). "The current genetic association study measured the allele frequencies of LOF and GOF SNPs of the P2X7 gene (P2RX7) in intensive care unit (ICU) patients who were either non-septic or suffered from sepsis, septic shock, with and without pneumonia." (PMID 38966639, 2024). "This was also confirmed for other cytokines, chemokines and acute phase proteins measured in the serum of P2rx7−/− mice as well as in wild-type mice treated with A438079, which suggests that P2X7 receptor is important for the downregulation of cytokines during sepsis." (PMID 33135636, 2020). "Here, we show that TLR2, TLR4, CD36, P2RX7, VIMP, and SCARB1 are also expressed in myocytes and muscle and that muscular expression of TLR2, TLR4, CD36, and VIMP increases during sepsis." (PMID 31441598, 2020).
Alzheimer disease (42 papers, 2012 to 2026). A progressive, neurodegenerative disease characterized by loss of function and death of nerve cells in several areas of the brain leading to loss of cognitive function such as memory and language. "P2x purinoreceptor 7 (P2RX7), an ATP-gated ion channel, is known to play pivotal roles in the progression of Alzheimer’s disease (AD), although its cell type-specific pathological mechanisms have yet to be elucidated." (PMID 40678243, 2025). "Specifically, dual NMDA-P2RX7 compounds were recently synthesized for targeting both the excitotoxicity-induced cell death as well as the P2RX7-dependent neuroinflammatory-induced cell death seen in Alzheimer's disease." (PMID 30003075, 2018).